TMEM247 (transmembrane protein 247)
Tractability: Antibody: UniProt predicts a signal peptide or a membrane-spanning region.
Gene: Protein-coding gene on chromosome 2 (46,479,565 to 46,484,425, forward strand). Ensembl gene ENSG00000284701.
Subcellular location: Membrane
Gene Ontology:
Cellular component: endoplasmic reticulum; membrane
Genetic constraint (gnomAD): Loss-of-function variants: 20 observed, 19.64 expected, observed/expected ratio (o/e) 1.02, 90% interval 0.71 to 1.48. The upper end of that interval is the gene's LOEUF score, 1.48, which puts it in group 6 of 6, group 1 being the genes least tolerant of losing a copy. Missense variants: 349 observed, 292.28 expected, observed/expected ratio (o/e) 1.19, 90% interval 1.09 to 1.3. Synonymous variants: 105 observed, 113.84 expected, observed/expected ratio (o/e) 0.92, 90% interval 0.79 to 1.09.
Homologues: Orthologues: macaque TMEM247 (96% identical), chimpanzee TMEM247 (95% identical), dog TMEM247 (78% identical), rat Tmem247 (68% identical), mouse Tmem247 (66% identical), rabbit TMEM247 (63% identical).